NPY (neuropeptide Y)
Diseases named in the same sentence as NPY in open-access papers (continued):
Sharing a sentence is not in itself a finding about the gene and the disease.
alcohol dependence (continued). "The present study found no significant relation between NPY rs16139 variant and alcoholism in either allelic or dominant models." (PMID 34777047, 2021). "Later, a systematic analysis of the NPY gene and its receptor revealed that polymorphisms in the NPY gene are not linked to alcoholism or AWS." (PMID 34777047, 2021). "Additionally, Neuropeptide Y (NPY) is a neuromodulator that is involved in the regulation of alcohol dependence and withdrawal, as well as the BDNF." (PMID 29896126, 2018). "The primary goal of this research was to investigate the effects of ACD intoxication and withdrawal by recording rat behavior and by measuring NPY immunoreactivity in hippocampus and NAcc, two brain regions mainly involved in processes which encompass neuroplasticity in alcohol dependence." (PMID 25324788, 2014). "The effects of ACD intoxication and withdrawal were investigated by recording rat behavior, and by measuring NPY expression in the hippocampus and ventral striatum, two of the brain regions mainly involved in processes which encompass neuroplasticity in alcohol dependence." (PMID 25324788, 2014). "Alcohol drinking behavior has been related to profound modifications in the transductional processes in NAcc neurons that are correlated to lower expression of NPY gene." (PMID 25324788, 2014). "A series of t-tests were then conducted to examine whether male inpatients with and without alcohol dependence and depressive symptoms differed in terms of the polymorphism NPY rs16147:T>C." (PMID 36245887, 2022). "In addition, NPY may play a key role in modulating the development of alcohol dependence." (PMID 37836499, 2023). "In animal models, NPY reduces stress effects and alcohol consumption, and opposes the actions of corticotropin-releasing factor (CRF) as well as responsible for the anxiogenic and stress-like consequences of alcohol dependence withdrawal." (PMID 36245887, 2022). "However, NPY and nociceptin decreased presynaptic GABA release in CeA, normalizing the enhanced GABAergic transmission observed in alcohol dependence." (PMID 30990816, 2019).
itch (14 papers, 2020 to 2025). "Neuropeptides, specifically SP and Neuropeptide Y (NPY), have been implicated in the pruritus found in psoriasis." (PMID 35321329, 2022). "Computational modeling identified that reduced expression of Nav1.6 in NPY+ neurons could be a key mechanism underlying the sensitization of this spinal circuit in chronic itch at the single-neuron and network levels." (PMID 35782385, 2022). "First, we assessed the necessity of the NPY-Y1R-signaling pathway in DRGVGLUT3-mediated itch inhibition." (PMID 41029777, 2025). "A recent study showed that chemogenetically activating NPY+ neurons reduced pruritogen-evoked itch behavior tested in the leg area." (PMID 41029777, 2025). "Nonetheless, our findings demonstrate that both NPY-INs and Dyn-INs contribute to the suppression of pruritogen-evoked itch thus revealing an overlap of function of these neurochemically distinct inhibitory interneuron populations." (PMID 37490401, 2023). "In patients with AD, elevated serum levels of neuropeptide Y (NPY) and increased serum VIP levels are associated with pruritus." (PMID 36983094, 2023). "NPY, on the other hand is found at lower levels in psoriatic patients with pruritus, which is possibly explained by the finding that it suppresses mechanical itch transmission in wild-type mice." (PMID 35321329, 2022). "Our model populations are currently simulating the most excitable subset of our experimentally measured Ucn3+ and NPY+ neurons in both control and chronic itch groups." (PMID 35782385, 2022). "We observed several concurrent changes in the AP properties and ion channel expression levels of Ucn3+ and NPY+ neurons under chronic itch conditions." (PMID 35782385, 2022). "Our experimental recordings demonstrated that Ucn3+ mechanical itch transmission neurons in the dorsal spinal cord become more excitable under chronic itch conditions, while NPY+ inhibitory gating neurons in the dorsal spinal cord become less excitable." (PMID 35782385, 2022). "Our models demonstrated that changes in Nav1.6 conductance are predominantly responsible for the changes in excitability of both Ucn3+ and NPY+ neurons during chronic itch pathogenesis." (PMID 35782385, 2022). "By contrast, the expression levels of Nav1.6 and BK channels were decreased in spinal NPY+ neurons in chronic itch mice." (PMID 35782385, 2022). "Increased serum VIP levels are correlated with pruritus and enhanced serum neuropeptide Y (NPY) levels are observed in patients with AD." (PMID 34281281, 2021). "This study was designed to investigate the role of NPY in aging-induced itch using the senile mouse model." (PMID 34122040, 2021). "While a recent study reported that NPY+ interneurons are also involved in gating the transmission of chemical itch signals, the regulatory effects of NPY+ neurons on different types of itch remain controversial." (PMID 41029777, 2025). "Intriguingly, recent insights further reveal a critical intersection of this system with pruritus: opioid drugs induce itch by suppressing the gating of GRP+ neurons by NPY+ neurons, thereby disinhibiting the GRP-GRPR itch circuit—a disruption that directly triggers pruritic responses." (PMID 41248150, 2025). "Meanwhile, it needs further investigation whether synapses or NPY in the synapses between Npy neurons and Tac2 neurons decrease during chronic itch." (PMID 38164144, 2024). "Upon light touch stimulation, excessive release of Zn2+ into the synaptic cleft disrupts the inhibitory effect exerted by NPY+-derived inhibitory INs on mechanical itch-transmitting neurons, thereby facilitating the generation of both aging-related itch and xerosis-related itch." (PMID 39602426, 2024). "NPY is a neuropeptide that is known to play an important role in pruritus but has not been previously associated with urticaria." (PMID 37795408, 2023). "It was observed that serum NPY levels were lower in psoriasis patients with pruritus." (PMID 37795408, 2023).
itch (continued). "Here, we show that activating NPY cells also strongly suppresses CQ-evoked itch." (PMID 37490401, 2023). "Our modeling results indicate that Nav1.6 may be the major component to alter excitability in both Ucn3+ and NPY+ neurons under chronic itch conditions." (PMID 35782385, 2022). "Next, we examined whether the excitability of NPY+ neurons was altered under chronic itch conditions." (PMID 35782385, 2022). "Our results suggest that decreased Nav1.6 conductance in NPY+ neurons may play the major role in sensitizing the mechanical itch circuit under chronic itch conditions." (PMID 35782385, 2022). "Novel therapeutics aimed toward upregulating the expression of Nav1.6 channel or augmenting the activity of existing Nav1.6 channels in NPY+ mechanical itch gating neurons may be worth exploring for managing chronic itch conditions." (PMID 35782385, 2022). "We marked NPY+ neurons in the dorsal spinal cord by crossing NPYCre and Ai14 strains and then recorded tdTomato+ neurons in spinal cord slices in control and calcipotriol-treated chronic itch mice." (PMID 35782385, 2022). "In NPY+ neurons, the expression levels of Nav1.6 and BK channels decreased in chronic itch mice." (PMID 35782385, 2022). "Unexpectedly, decreased plasma levels of NPY in patients with pruritus were observed." (PMID 33467067, 2021). "Bhlhb5-dependent interneurons gate chemical itch while NPY+ interneurons gate mechanical itch." (PMID 33050211, 2020). "In this study, we used a combination of electrophysiological recording, single-cell qRT-PCR and computational modeling to reveal that reduced Nav1.6 conductance in spinal NPY+ inhibitory interneurons may play a major role in sensitizing mechanical itch pathways under chronic itch conditions." (PMID 35782385, 2022). "Both spontaneous and CQ-evoked itch behaviours were suppressed when GRPR and NPY cells were silenced simultaneously, and we show directly, using both anatomical and electrophysiological methods, that the NPY cells provide a strong inhibitory input to GRPR-INs." (PMID 37490401, 2023). "Recent studies also indicated the specific role of spinal NPY in gating mechanical itch signal, but not chemical itch signal." (PMID 34122040, 2021). "A previous study reported that plasma levels of neuropeptide Y (NPY) were significantly lower in psoriatic patients with than in those without pruritus." (PMID 33182442, 2020). "In one study, the serum NPY values of psoriasis patients with and without pruritus were compared." (PMID 37795408, 2023). "We propose that the lack of spinal NPY may be involved in certain types of pruritus in the elderly population." (PMID 34122040, 2021). "Indeed, in the chemical itch model, blocking the NPY-Y1R-signaling pathway does not diminish the itch inhibition mediated by VGLUT3+ sensory fibers (histamine: t = 0.3059, p = 0.7641, two-tailed unpaired t test; chloroquine: t = 0.02711, p = 0.9787, two-tailed unpaired t test)." (PMID 41029777, 2025).
Hypoglycemia (13 papers, 2011 to 2025). A decreased concentration of glucose in the blood. "Previous behavioural data also support a role for NPY neurons in the feeding response to hypoglycemia with animals genetically deficient in NPY displaying reduced glucoprivic feeding." (PMID 21440571, 2011). "Recent studies have shown that ARC-projecting TH+ catecholamine neurons in the NTS mediate hypoglycemia-induced feeding and that TH+/NPY+ NTS neurons stimulate feeding." (PMID 38246589, 2024). "However, after three episodes of hypoglycaemia, TH immunoreactivity was consistent with basal levels, reportedly due to the inhibitory effects of NPY on TH expression leading to reduced adrenaline response." (PMID 38392992, 2024). "Major populations of neuropeptide Y (NPY)-expressing neurons are located in the arcuate nucleus, with another in the nearby lateral hypothalamus that intrinsically sense extracellular glucose and respond to insulin-induced hypoglycemia." (PMID 32193527, 2020). "Activated microglia were found in close apposition to hypoglycemia-responsive NPY neurons." (PMID 30996341, 2019). "While there are very few studies which have investigated the effects of insulin-induced hypoglycaemia on neuropeptides in the adrenal gland, current evidence suggests that recurrent insulin-induced hypoglycaemia increases protein expression of neuropeptides such as NPY, galanin, and proenkephalin." (PMID 38392992, 2024). "Confocal microscopic analysis of hypothalamic sections revealed that IBA1 positive microglia are recruited in close apposition to hypoglycemia-activated c-FOS positive, NPY neurons." (PMID 30996341, 2019). "Conversely, under hypoglycemic conditions, aberrant microglial activation interacts with orexigenic neuropeptide Y (NPY) neurons to suppress HPA axis activity, and microglial inhibition enhances counterregulatory responses to both insulin-induced and neurogenic hypoglycemia." (PMID 41294833, 2025). "Our data suggest that GK within these specific feeding and arousal related populations of AgRP/NPY and ORX neurons may play a modulatory role in the sensing of and appetitive response to hypoglycaemia." (PMID 21440571, 2011). "Moreover, individuals with long-duration T1D are complicated with autonomic neuropathy when they have markedly reduced or absent responses of NPY to insulin-induced hypoglycemia." (PMID 35627254, 2022). "In experimental animals, NPY neurons in the ARC are activated by negative metabolic challenges, such as fasting and hypoglycemia and NPY signaling is required to stimulate hepatic glucose production in response to a decrease in plasma glucose levels." (PMID 22808091, 2012).
anxiety disorder (12 papers, 2013 to 2025). A category of psychiatric disorders which are characterized by anxious feelings or fear often accompanied by physical symptoms associated with anxiety. "The Neuropeptide Y (NPY) gene has been implicated as a potential risk factor for anxiety disorders, including PTSD." (PMID 37626936, 2023). "Neuropeptide Y (NPY) had modulating effect on stress exposure on susceptibility to anxiety disorders in both animal models and human studies." (PMID 31435520, 2018). "Neuropeptide Y (NPY) has been implicated in feeding and, recently, has been identified as a potential target for the treatment of anxiety disorders." (PMID 26441567, 2015). "Moreover, the outcome has a meaning for the understanding of the stress response in OCD in general which might be different from other anxiety disorders with an association to NPY." (PMID 31133798, 2019). "The NPY detection platform is envisioned to be a wearable point-of need monitoring system for management of chronic anxiety disorders and MDD." (PMID 35520310, 2020). "Neuropeptide Y (NPY) biomarker levels have a close association with the diagnosis of Major Depression Disorder (MDD) and anxiety disorders." (PMID 35520310, 2020). "This difference in NPY gene expression can therefore contribute to anxiety disorders, including panic disorder." (PMID 31435520, 2018). "Furthermore, NPY also affects sleep regulation and circadian rhythms and is involved in various nervous system processes and neuropsychiatric disorders, such as anxiety disorders." (PMID 40989139, 2025). "We only know so far that NPY is involved in stress and other anxiety disorders." (PMID 31133798, 2019). "Interestingly, previous studies have demonstrated that in addition to NPY-ergic system, BDNF also interacts with the HPA axis, and therefore, it has been implicated in the etiology of anxiety disorders and PTSD." (PMID 26016844, 2015). "The first aim of the current project was to elucidate peripheral changes in plasma-derived IL-6, TNF-β, NPY, and DPPIV in two common anxiety disorders in child and adolescent psychiatry, SM and SAD, in comparison to a control group (CG)." (PMID 34267682, 2021). "Overall, findings on plasma NPY concentrations and their relation to circulating DPPIV in the context of anxiety disorders must be interpreted with caution, and our present results need to be confirmed in larger follow-up studies." (PMID 34267682, 2021).
Huntington disease (12 papers, 2011 to 2025). Huntington disease (HD) is a rare neurodegenerative disorder of the central nervous system characterized by unwanted choreatic movements, behavioral and psychiatric disturbances and dementia. "The stimulation of Y2 receptors by NPY has been shown to increase BDNF level associated with improvement of motor function in a mouse model of Huntington disease." (PMID 31281833, 2019). "The Neuropeptide Y (NPY) is a 36‐residue‐long peptide that has been associated with a variety of neuroprotective effects in PD and other neurodegenerative disorders such as AD and Huntington's disease." (PMID 39720890, 2025). "Indeed, it was previously shown that intranasal NPY ameliorates motor and neuropathology deficits and extends life span of Huntington’s disease transgenic mice." (PMID 33558582, 2021). "Studies have also shown that NPY is involved in the pathogenesis of Huntington's disease (HD)." (PMID 34422139, 2021). "Recent studies demonstrate exciting potential of intranasal NPY or selective agonists to attenuate the development of immune-challenge and stress-elicited behavioral changes, as well as neurodegenerative diseases like Huntington’s disease." (PMID 32867327, 2020). "Furthermore, intranasal NPY attenuated impaired locomotion and exploration in immune-challenged mice and disease pathology in a mouse model of Huntington’s disease." (PMID 32867327, 2020). "In the central nervous system, NPY has been proven to control and alleviate neurodegeneration in models of Parkinson’s disease (PD), Huntington disease (HD), and Alzheimer’s disease (AD)." (PMID 35185528, 2022). "Interestingly, a reduced expression of NPY in the hilus of R6/2 mice was observed, accompanied by a reduction in the number of Y1R positive cells in the DG, thus suggesting that alterations in the NPY system might contribute to the impairment of neurogenesis in this model of Huntington disease." (PMID 25852477, 2015). "NPY is also involved in the prevention of negative consequences of stress, which is a factor that contributes to neurodegenerative diseases such as Alzheimer’s, Parkinson’s, and Huntington’s disease." (PMID 37836499, 2023).
osteoarthritis (12 papers, 2017 to 2025). A noninflammatory degenerative joint disease occurring chiefly in older persons, characterized by degeneration of the articular cartilage, hypertrophy of bone at the margins and changes in the synovial membrane. "Osteocyte NPY is a key factor in the pathogenesis of osteoarthritis, and IF can reduce the expression level of NPY in osteocytes." (PMID 40761349, 2025). "Osteocytes, the most abundant bone cells, secrete excess neuropeptide Y (NPY) to promote the development of osteoarthritis by directly or indirectly stimulating inflammation, osteoclast formation, and sensory nerve outgrowth." (PMID 38978353, 2024). "Osteocytes, the most abundant bone cells, secrete excess neuropeptide Y (NPY) during osteoarthritis, and this alteration can be altered by intermittent fasting." (PMID 38978353, 2024). "In our study, we identified osteocyte NPY as a key regulator that orchestrated most pathological changes during osteoarthritis, including inflammation, robust osteoclast formation, excessive sensory innervation, and cartilage degeneration." (PMID 38978353, 2024). "Our study aimed to provide detailed evidence for the protective benefits of intermittent fasting on osteoarthritis and uncover the role of osteocyte NPY during this process." (PMID 38978353, 2024). "Suri and colleagues have localized both sensory (SP- and CGRP-positive) and sympathetic (NPY-positive) nerve fibers in the articular cartilage in human tibiofemoral osteoarthritis." (PMID 35761305, 2022). "NPY is also a local regulator of osteoblastic lineage and is responsive to mechanical stimuli with potential roles in fracture healing and osteoarthritis." (PMID 34440365, 2021). "Results in our study revealed that osteocyte NPY was a multiple pathological processes‐involving molecule during osteoarthritis and could serve as a therapeutic target for osteoarthritis." (PMID 38978353, 2024). "Next, we assessed whether osteocyte NPY production was augmented during osteoarthritis and whether this alteration could be altered by intermittent fasting." (PMID 38978353, 2024). "Interestingly, the VAS score correlated positively with MOD values of CGRP, SP, and VIP, and negatively with MOD values of NPY in all patients, although a significantly higher expression was observed in patients with osteoarthritis." (PMID 35566735, 2022). "Depletion of osteocyte NPY significantly attenuates DMM‐induced osteoarthritis and abolishes the benefits of intermittent fasting on osteoarthritis." (PMID 38978353, 2024). "This study suggests that osteocyte NPY is a key contributing factor in the pathogenesis of osteoarthritis and intermittent fasting represents a promising nonpharmacological antiosteoarthritis method by targeting osteocyte NPY." (PMID 38978353, 2024). "Intermittent fasting potently relieves osteoarthritis by suppressing the generation of osteocyte NPY and represents a promising nonpharmacological antiosteoarthritis strategy." (PMID 38978353, 2024). "To examine the involvement of NPY in the development of osteoarthritis and the antiosteoarthritic effects of intermittent fasting, we first tested the expression changes of NPY in DMM‐induced osteoarthritis mouse models." (PMID 38978353, 2024). "It is known that an increase of NPY in the DRG and the spinal cord is followed after peripheral nerve injury and osteoarthritis but not after painful inflammation." (PMID 31023212, 2019).